USP14 (ubiquitin specific peptidase 14)
Diseases named in the same sentence as USP14 in open-access papers (continued):
Sharing a sentence is not in itself a finding about the gene and the disease.
retinal degeneration (1 paper, 2020). Degeneration of the retina. "Drosophila USP14 protects cell from ER stress triggered by ER stress-causing chemicals Drosophila S2 cells and suppresses the retinal degeneration in disease model for retinitis pigmentosa by regulating the stability of Rhodopsin-1." (PMID 33053617, 2020). "The USP14-expressing ninaEG69D/+ flies demonstrated a delayed course of retinal degeneration with approximately 67% of flies exhibiting intact Rh1>GFP patterns (67.1 ± 4.079%, p < 0.001)." (PMID 33053617, 2020). "A similar effect of USP14 on retinal degeneration was evident in female flies, although the rate of retinal degeneration in females was delayed compared to that in males." (PMID 33053617, 2020). "Significantly, the expression of USP14 in the ninaEG69D/+ background resulted in a delayed course of retinal degeneration with approximately 56% of the examined flies (p < 0.01) exhibiting pseudopupil on day 44 (red line)." (PMID 33053617, 2020). "In this study, USP14 also regulated the stability of Rh-1 and suppressed the retinal degeneration in a Drosophila ADRP model." (PMID 33053617, 2020). "Finally, USP14 contributes to the suppression of retinal degeneration in a Drosophila model of ADRP." (PMID 33053617, 2020).
α-synucleinopathies (1 paper, 2024). "Mechanistically, Usp14 deficiency enhanced the expressions of heterodimeric protein S100A8/A9 in the substantia nigra (SN) of mouse models with α-synucleinopathies." (PMID 38780644, 2024). "Mechanistically, the heterodimeric protein S100A8/A9 may be the downstream target of Usp14 deficiency in female mouse models of α-synucleinopathies." (PMID 38780644, 2024).
cancer (106 papers, 2008 to 2026). A tumor composed of atypical neoplastic, often pleomorphic cells that invade other tissues. "Although many reports have shown that highly expressed USP14 promotes cancer cell proliferation via the Wnt/β-catenin pathway and is associated with metastasis, the substrates and mechanism of USP14 as an oncogene still need to be explored." (PMID 36693850, 2023). "Ubiquitin-specific protease 14 (USP14), as one of the proteasome-associated deubiquitinase, exerts important roles in several carcinomas." (PMID 36423684, 2022). "Through a metabolomic analysis, we found that inhibition of FASN demonstrated very different metabolic profiles from inhibition of USP14, indicating that these enzymes have little association with cancer cell metabolism." (PMID 34948233, 2021). "In some cancers (colon, lung and ovarian), USP14 is implicated as an oncoprotein that can be responsible for metastization and tumoral growth." (PMID 34577547, 2021). "USP14 overexpression is associated with diverse diseases, and due to this, a reduction in its levels or activity can be promising as a cancer therapy strategy." (PMID 34577547, 2021). "Apart from its neurological implication, emerging evidence also suggests that USP14 is highly overexpressed in several cancers, and often associated with tumor relapse and metastasis." (PMID 34207520, 2021). "As a result, USP14 overexpression reduced enzymatic activity of FASN, whereas USP14 deficiency significantly increased FASN activity in cancer cells." (PMID 34948233, 2021). "USP14 is often associated with oncogenic function, since this enzyme is overexpressed in several cancers and is positively correlated with tumor recurrence and poor prognosis." (PMID 32726943, 2020). "Among the DUBs that have been identified in the human genome, USP14 has been implicated in several types of cancers, including brain, ovarian, and liver cancers." (PMID 31013812, 2019). "AKR1B10 has been previously reported as a potential diagnostic marker specific to smokers' NSCLCs, while USP14 was reported to be over-expressed in various types of cancer, including NSCLC." (PMID 29285267, 2017). "We have recently demonstrated that Aur mainly targets proteasome-associated UCHL5 and USP14 and thereby induces proteasome inhibition, caspase activation and apoptosis in several cancer cell lines." (PMID 26625200, 2016). "So far, not much is known regarding the transcriptional regulation of USP14 or any mutations in the gene that could affect its expression in different models of cancer." (PMID 37711852, 2023). "Alterations in cellular levels of USP14 levels have been associated with different types of cancer." (PMID 37711852, 2023). "However, in most cases, the underlying mechanisms of USP14 inhibitor for cancer treatment remain largely elusive." (PMID 34207520, 2021). "Studies on the expression of USP14 also assumed that USP14 was associated with cancer progression." (PMID 27448976, 2017). "Phosphorylation and activation of USP14 mediated by Akt may provide a mechanism for promoting tumorigenesis in cancer cells with PTEN loss." (PMID 29039082, 2017). "We examined whether USP14-induced inhibition of autophagy induction was associated with capacity of cancer migration and invasion." (PMID 29326710, 2017). "Among these DUBs, POH1, UCHL5 and USP14 are associated with the 19S proteasome; they are often overexpressed in several carcinoma cells, which renders them potentially new therapeutic targets in these cancer cells." (PMID 26625200, 2016). "To date, only a few studies have implicated USP14 in cancer." (PMID 23702845, 2013). "Indeed, overexpression of USP14 is associated with poor survival in a variety of cancers." (PMID 31740976, 2020). "In addition to RPN11, UCHL5 and USP14 are also associated with cellsurvival and cancer progession." (PMID 24977961, 2014). "To date, multiple signaling pathways in which USP14 mediates cancer progression and chemotherapy resistance have been identified." (PMID 39928282, 2025).
cancer (continued). "USP14 knockdown significantly reduced cancer cell proliferation by 20% (LoVo) and 25% (SW48) and clonogenic potential by 60% (LoVo) and 69% (SW48), as confirmed by colony formation and EDU assays." (PMID 40316942, 2025). "To extend these findings to an in vivo context, we employed xenograft models in which cancer cells with USP14 knockdown were subcutaneously injected into nude mice." (PMID 40316942, 2025). "We investigated USP14’s impact on cancer cell sensitivity to the chemotherapeutic agent oxaliplatin." (PMID 40316942, 2025). "This discovery enriches the existing knowledge of the significant impact of USP14 in the field of cancer research." (PMID 39928282, 2025). "In these cancers, USP14 and UCHL5 have been shown to stabilize crucial oncogenic proteins and promote tumor progression." (PMID 40804247, 2025). "Targeting the USP14/BAG4/PRKN axis to enhance mitophagy shows promise for improving cancer treatment efficacy." (PMID 40316942, 2025). "Upon USP14 knockdown, cancer cells exhibited a significantly enhanced response to oxaliplatin treatment, as evidenced by a marked increase in apoptosis by 37% (LoVo) and 25% (SW48)." (PMID 40316942, 2025). "Knockdown of USP14 or treatment with a USP14-specific inhibitor (IU1) led to significantly increased BAG4 ubiquitination levels in cancer cells, implying that USP14 normally functions to deubiquitinate BAG4 and prevent its degradation." (PMID 40316942, 2025). "Results from CCK8 and EDU assays revealed that silencing USP14 significantly suppressed cancer cell proliferation, while BAG4 overexpression rescued this effect." (PMID 40316942, 2025). "Overexpression of USP14 caused a dose-dependent increase in BAG4 protein, while knockdown of USP14 in cancer cells resulted in a marked reduction in BAG4 protein levels." (PMID 40316942, 2025). "Several studies have indicated that USP14 promotes radioresistance by regulating autophagy or DNA repair in various cancers." (PMID 40595451, 2025). "USP14, a deubiquitinating enzyme, has garnered significant attention for its role in cancer progression, as it influences multiple cellular processes including protein degradation, cell cycle regulation, and apoptosis." (PMID 40374593, 2025). "Numerous studies have shown that USP14 is amplified and overexpressed in various types of malignant tumors." (PMID 38819674, 2024). "The abnormal activity of USP14 is closely related to the initiation, development, and drug resistance of cancer." (PMID 38819674, 2024). "We screened DUBs to identify a protein responsible for regulating VSMC proliferation and identified USP14 protein that mediates cancer development, inflammation, and foam cell formation." (PMID 38909015, 2024). "By stabilizing CIB1 through deubiquitination, which facilitates the MAPK signaling cascade, USP14 enables sustained signaling despite the presence of lenvatinib, ultimately promoting cancer cell survival and proliferation." (PMID 38993552, 2024). "The expression of USP14 is negatively correlated with prognosis, which plays a crucial role in cancer development and has been recognized as a new therapeutic target for cancer." (PMID 38819674, 2024). "USP14 plays an oncogenic role in various types of cancer, and its inhibitors have shown significant effects in a variety of anticancer studies." (PMID 38819674, 2024). "The coding gene for USP14 is located on human chromosome 18p11.32, and studies have found that this region is closely related to the regulation of human malignant tumors." (PMID 38388430, 2024). "Studies have shown that USP14 is overexpressed in a variety of cancers and neurodegenerative diseases, which plays an important regulatory role in cell activities such as cell proliferation and apoptosis, DNA damage repair, and signaling transduction." (PMID 38819674, 2024). "Among the top positive proteins, USP14 was found to be closely related to malignant tumor development." (PMID 37046655, 2023).
cancer (continued). "In view of its importance for cell viability and proliferation, strategies targeting USP14 have been explored with the aim to influence protein degradation in cancer cells." (PMID 37711852, 2023). "We first observed that protein levels of USP14 were lower in the ML1 cancer cells in comparison with the control primary thyroid cells." (PMID 37711852, 2023). "In vitro and in vivo functional experiments confirmed that USP14 was a driver of cancer progression and liver metastasis in PDAC." (PMID 35906484, 2023). "As one of the main members of ubiquitin proteasome system, USP14 has attracted much attention because of its important role in a variety of cancers." (PMID 37082728, 2023). "Ubiquitin‐specific protease (USP14) is involved in various pathological conditions including cancer; however, the role of USP14 in NSCLC remains elusive." (PMID 37035133, 2023). "In prostate cancer, USP14 regulates cancer cell proliferation by deubiquitinating and stabilizing androgen receptors." (PMID 36693850, 2023). "Among 16 cancer-related pathways, a high expression of USP14 was found to mainly activate the HSF1 pathway." (PMID 37686660, 2023). "In confirmation of the transcriptomic results, we observed increased USP14 protein expression in cancer tissue from both the oral cavity and other subsides of the head and neck when compared to normal oral tissue." (PMID 37055579, 2023). "Conversely, IDO1 knockdown restored the percentage of Granzyme B+ CD8+ T cells and reduced the frequency of CD25+FOXP3+ CD4+ T cells within tumor tissues derived from USP14-overexpressing cancer cells." (PMID 37830596, 2023). "USP14 ablation reduces cancer cell proliferation in vitro and colorectal tumorigenesis in vivo by downregulating MAPK/JNK pathway activation." (PMID 36693850, 2023). "A previous study has highlighted that USP14 contributed to cell growth, migration, the activation of kinase and inflammasome, as well as inhibited autophagy and apoptosis in cancer cells." (PMID 37082728, 2023). "Considering the pathogenic effects of USP14 in cancer and other diseases, several studies have described the development of small molecule inhibitors (SMI) that target USP14 69-71." (PMID 37496999, 2023). "IU1 (another USP14 inhibitor) restrains the activity of cancer-promoting macrophages by inhibiting fatty acid metabolism; capzimin (an RPN11inhibitor) stabilizes the substrate and presents anti-proliferative effects on tumor cells." (PMID 37190313, 2023). "USP14 is highly expressed in a variety of malignant tumors, and its action mechanism remains indistinct and complex, which covers the basic biological events in tumors 9-11." (PMID 37082728, 2023). "IHC assays with 43 paired HNSCC patient tissue chips revealed a higher expression of USP14 in HNSCC tissues than in para-carcinoma tissues." (PMID 37686660, 2023). "Generally, USP14 is a promising drug target for cancer therapy, especially in patients with high IDO1 expression." (PMID 36163134, 2022). "USP14 is another highly studied, proteasome-bound DUB considered to be a promising therapeutic target in some cancers and USP14 has been reported to rescue many proteins from degradation by the proteasome." (PMID 35737447, 2022). "Due to the potential of therapeutic target in various cancers, several USP14 inhibitors have been gradually developed to confirm their effect." (PMID 36582601, 2022). "For example, USP14 is a component of the proteasome and considered to be a promising therapeutic target in cancer due to the clinical success of other proteasome inhibitors." (PMID 35737447, 2022). "It has been reported that USP14 is highly related to cancer occurrence and progression in various kinds of carcinomas." (PMID 36423684, 2022). "Consistent with its physiological and pathophysiological role in several important signaling pathways, USP14 has emerged as a drug target in a wide range of malignancies, including cancer and neurodegenerative diseases." (PMID 35069211, 2021).
cancer (continued). "Since Usp14 regulates the level of FASN in MPHs, we predicted that knockdown or inhibition of FASN and USP14 together would have a synergistic effect in reducing the proliferation of cancer cells." (PMID 34948233, 2021). "In terms of WNT/β-catenin signaling, USP14 is overexpressed in lung adenocarcinoma and promotes cancer cell proliferation by upregulating β-catenin." (PMID 34179009, 2021). "In summary, the research on USP14 has made great progress in delineating its roles in the proliferation, migration and autophagy of different cancer cells." (PMID 34179009, 2021). "Further studies should be conducted to find direct targets of USP14 that can control FASN levels in cancer cells." (PMID 34948233, 2021). "Ubiquitin‐specific protease 14 (USP14) has emerged as a critical regulator in the development of human cancers and neurodegenerative diseases." (PMID 34089575, 2021). "USP14 has been investigated as a potential therapeutic target to treat neurodegenerative disorders and cancers." (PMID 34207520, 2021). "USP14 inhibitors, for example, have been attempted to treat a variety of disease models including neurodegenerative diseases, cancers, and others." (PMID 34207520, 2021). "Ub-specific protease 14 (USP14), another DUB, has been implicated in the tumorigenesis and progression of several cancers." (PMID 34070986, 2021). "Accumulating evidence has demonstrated that USP14 is involved in the occurrence and development of various human cancers." (PMID 34089575, 2021). "UALCAN online tool analysis demonstrated a significant correlation between USP14 mRNA expression and clinical cancer stages and histological grades." (PMID 34420039, 2021). "We therefore attempted to effectively inhibit cancer cell growth by using a FASN inhibitor in combination with an inhibitor of a deubiquitinating enzyme USP14, which is known to maintain FASN protein levels in hepatocytes." (PMID 34948233, 2021). "In drug-resistant cancer cells, inhibitors of UCHL5 and USP14 mitigate resistance and sensitize cancer cells to cell death by modulating diverse cellular mechanisms." (PMID 33919439, 2021). "Several types of cancers are sensitized to cell death by depleting or pharmacological inhibition of UCHL5/USP14." (PMID 33919439, 2021). "Although USP14 inhibitors have also been shown to be useful in cancer treatment, broad space for research on USP14 with respect to ITAIM regulation remains open because of its activation and upregulation of SRS." (PMID 34179009, 2021). "Accordingly, genetic downregulation or chemical inhibition of USP14 displayed anti-proliferative effects in a number of cancer models." (PMID 34207520, 2021). "USP14 expression is upregulated in various cancers, and the oncogenic effect of USP14 has been widely reported." (PMID 34948233, 2021). "The deubiquitination of USP14 inhibits the autophagic occurrence, and USP14 expression is increased in a variety of cancers, these studies make USP14 a potential approach to cancer treatment." (PMID 33281606, 2020). "Though USP14 is more pronounced for its therapeutic potential in cancer, its role in neurodegenerative disorders is also known." (PMID 32850842, 2020). "Taken together, these data establish that elevated AKT signalling plays a critical role in regulating the function of USP14 in DSB repair in PTEN- and autophagy-deficient cancer cells." (PMID 31740976, 2020). "More specifically, elevated USP14 expression has been found in various cancer types, including lung, breast and gastric cancers, pancreatic adenocarcinomas, and esophageal squamous cell carcinoma." (PMID 32726943, 2020). "USP14 was overexpressed in many cancers and promoted tumor cell proliferation through enhancing β-catenin accumulation and inhibiting Bcl-xl-mediated cell apoptosis." (PMID 30425250, 2018). "A previous study revealed that USP14 modulates cancer cell motility by deubiquitinating the chemokine receptor CXCR4." (PMID 27448976, 2017).